VEGFA (vascular endothelial growth factor A)
Diseases named in the same sentence as VEGFA in open-access papers (continued):
Sharing a sentence is not in itself a finding about the gene and the disease.
tumor (continued). "Expression of matrix metalloproteases 2, 9 and 14 (MMP-2, MMP-9, MMP-14), tissue inhibitors of metalloprotease 1 and 2 (TIMP-1, TIMP-2) and vascular endothelial growth factor A (VEGF-A) is involved in tumor invasion and metastasis via extracellular matrix degradation and angiogenesis." (PMID 32669083, 2020). "In addition, miR-29a has been shown to play a key antiangiogenic role within the tumor microenvironment by suppressing the expression of VEGFA." (PMID 32733638, 2020). "In this respect, recent experimental data highlighted a direct effect of VEGFA on endothelial receptors that modifies T cell diapedesis and allows TRegs rather than T cytotoxic cells to migrate to the tumor bed, thus decreasing the tumor’s immune capacity." (PMID 33238394, 2020). "We assumed that Peptibody vaccine with dramatic immunogenicity could neutralize bFGF and VEGFA in tumor microenvironment via the anti‐bFGF and anti‐VEGFA antibodies it elicited." (PMID 32944017, 2020). "In addition, patients with high B7-H3 expression in tumor tissues had significantly higher VEGFA expression than patients with low B7-H3 expression." (PMID 31974361, 2020). "The ability to quantify the activity of membrane bound VEGFA in addition to soluble VEGF as shown herein may facilitate a better understanding of the action of bevacizumab on tumor-induced vascularization in both gynecologic and neurologic tumors." (PMID 33178180, 2020). "The expression levels of HIF-1α and VEGFA in tumor cells were similar to that of CD31." (PMID 32382013, 2020). "Thus, the mechanisms that regulates the expression or activating of VEGFA are critical for regulating tumor angiogenesis." (PMID 32070413, 2020). "In mouse model, the tumor growth and angiogenesis were suppressed by Peptibody vaccine, which could elicit superior immune responses of anti‐bFGF and anti‐VEGFA antibodies." (PMID 32944017, 2020). "Furthermore, our results revealed that B7-H3 promoted tumor angiogenesis by upregulating VEGFA expression in an NF-κB pathway-dependent manner." (PMID 31974361, 2020). "Importantly, histone methylation and its responsible methyltransferases or demethylases are indispensable for VEGFA and its receptors regulation and tumor angiogenesis." (PMID 32070413, 2020). "Interestingly, many of the tumor-derived ETC markers were upregulated in retinas following transient VEGFA treatment, whereas ESC markers were largely unperturbed." (PMID 31754927, 2020). "Our finding demonstrates that miR-106a-5p can be a reason for VEGFA upregulation in tumor cells." (PMID 33224312, 2020). "As B7-H3 promoted tumor angiogenesis in CRC via the NF-κB/VEGFA signaling pathway, we wondered whether B7-H3 blockade and BAY11–7082 or bevacizumab co-treatment exerts synergetic effects on the inhibition of angiogenesis in vivo." (PMID 31974361, 2020). "We thought targeting SerRS might be a better strategy than targeting VEGFA directly, because SerRS has a broader anti-tumor mechanism besides blocking angiogenesis, for example, SerRS can also promote tumor senescence." (PMID 32550907, 2020). "Interestingly, the correlation between VEGFA expression in tumor tissue and serum (r = 0.87, P < 0.05) was much stronger than between the levels in tumor tissue and plasma (r = 0.75, P = 0.153)." (PMID 32564774, 2020). "Moreover, VEGFA plays an important role among the mechanisms that occur in pituitary tumorigenesis, angiogenesis for tumor growth, and was proposed as pituitary proangiogenic factor and possible therapeutic target." (PMID 33362712, 2020). "In addition, other proteins related to tumor proliferation/invasion were similar to VEGFA (P < 0.01)." (PMID 33362712, 2020). "Among the tumor specimens with IDH mutation, mRNA levels of SEMA3B, SEMA3C, SEMA3D, SEMA3G, NRP2, PLXNA2, and CDH1 were significantly higher (p < 0.05), while SEMA3F, NRP1, ITGB3, ITGA5, and VEGFA genes were under-expressed (p < 0.05)." (PMID 33036421, 2020).
tumor (continued). "Finally, the effect of the lncRNA IRAIN/VEGFA axis was confirmed in an in vivo tumor xenograft model." (PMID 32983957, 2020). "Besides inducing tumor angiogenesis, VEGFA also facilitates chemotactic cell migration and increases vascular permeability." (PMID 33324652, 2020). "Neutrophils induce Bv8-dependent tumor angiogenesis independently from the VEGFA signaling." (PMID 32775327, 2020). "Similar, ZLM-7 could inhibit tumor growth and angiogenesis through the miR-212-3p/Sp1/VEGFA axis in vivo." (PMID 33187481, 2020). "In the fast-growing period, most solid tumors were hypoxic, these hypoxic tumor cells and some immune cells could secret pro-angiogenesis cytokines such as vascular endothelial growth factor A and growth factors, leading to tumor cell proliferation." (PMID 32134471, 2020). "As bevacizumab is an antibody that neutralizes the cytokine VEGFA, we wondered if the benefit from this agent could correlate with its tumor expression pattern." (PMID 32564774, 2020). "Interestingly, the vascular APLN RNA signal was highest in the tumor regions where human VEGFA RNA was also detected." (PMID 32545380, 2020). "MMP2 and VEGFA are both recognized as the molecular biomarkers of tumor angiogenesis." (PMID 32600379, 2020). "The deleterious effects of estrogen in hypoxia on ATM repression and HIF1A/VEGFA activation indicate that estrogen may also have pro-tumorigenic and pro-angiogenic effects deep within an hypoxic tumor." (PMID 33363037, 2020). "A very well studied molecule in tumor angiogenesis, VEGFA can be released by MDSCs." (PMID 32508809, 2020). "In addition, GC cells after omental stimulation transform to an angiogenic phenotype through HIF1α and VEGFA overexpression, which also induces tumour growth and invasion." (PMID 32439934, 2020). "Thus, conversion of pNK cells to a dNK-like phenotype (poor cytotoxic potential and elaboration of VEGFA expression) is favored by hypoxia; a factor with key roles in tumor invasion and metastasis and response to therapy." (PMID 32655841, 2020). "HIF1A and HK2 were important glycolysis regulated genes, VEGFA was tumor angiogenesis gene." (PMID 33197880, 2020). "So, increasing SerRS expression could be a promising strategy to inhibit abnormal VEGFA expression and tumor angiogenesis." (PMID 32944400, 2020). "HOXD10 also attenuates tumor angiogenesis via downregulation of angiogenic factors including VEGFA." (PMID 33171691, 2020). "In addition to the regulation of VEGFA or its receptor expression, HMTs also regulate PTMs of VEGFR1 or alternative splicing of VEGFA to affect tumor angiogenesis." (PMID 32070413, 2020). "Especially, TAMs with high expression of Tie2 aggregate around tumor blood vessels and are selectively activated into M2-like subpopulations following chemotherapy, which promote tumor blood vessel reconstruction and recurrence in a VEGFA-dependent manner." (PMID 33505964, 2020). "We speculated that, instead of cleaving protein substrates (including tumor mediators), calpain-6 would interact with VEGFA to promote VEGF secretion, which would enhance angiogenesis." (PMID 31673071, 2019). "However, inhibitors of VEGFA-mediated signaling often trigger limited responses in both human tumours and mouse models of cancer, due to the development of evasive and intrinsic resistance mechanisms." (PMID 30842454, 2019). "Among all miRNAs, miR-29c has been found to suppress tumor angiogenesis by targeting VEGFA." (PMID 30948500, 2019). "Furthermore, although CAFs are the major source for VEGFA in tumors, they can support tumor angiogenesis in a VEGFA-independent manner." (PMID 31484464, 2019). "Also, the combination of BI 885578 with a Vascular endothelial growth factor A (VEGF-A) antibody increased treatment efficacy and induced tumor regression." (PMID 31623387, 2019). "Inhibition of autophagy could enhance the anti-angiogenesis potential of anlotinib through the reduction of VEGFA production or secretion of tumor cells." (PMID 30755242, 2019).
tumor (continued). "Aberrant VEGFA or β2AR expression significantly affected EHD1-mediated tumor angiogenesis." (PMID 31023336, 2019). "In addition, the expression levels of PTEN, vimentin, and vascular endothelial growth factor-a (VEGFA) have been determined with the aim of obtaining further information regarding the tumor cells’ aggressiveness." (PMID 31453379, 2019). "If these adhesions play a functional role in anti-tumor lymphocyte recruitment, this may partially contribute to the limited effects of anti-VEGFA therapies." (PMID 31497019, 2019). "TAMs also secrete VEGFA, which promotes angiogenesis and supports tumor progression." (PMID 30651598, 2019). "Considering VEGFA functions as a key regulator in the process of tumor angiogenesis, we then explored whether there was an association between the expression of Akirin2 and VEGFA." (PMID 30886152, 2019). "Here, we evaluated the correlation between miRNA expression and VEGFA expression in tumour samples." (PMID 31277414, 2019). "Indeed, the angioinhibitory function of miR-150-5p is mediated by VEGFA suppression which subsequently leads to tumor growth inhibition in CRC." (PMID 31887997, 2019). "In addition to genome-wide CNA, we evaluated the association between VEGFA amplification in cfDNA and treatment outcomes based on a previous study suggesting VEGFA genomic amplification in HCC tumor tissues as a predictive biomarker for sorafenib." (PMID 30935424, 2019). "Hypoxia of growing tumor cells will induce the release of angiogenesis signals, such as vascular endothelial growth factor A (VEGFA), that induce angiogenesis response after binding to the VEGF receptor 2 (VEGFR-2) located at the surface of endothelial cells present in neighbor endothelial cells." (PMID 30781344, 2019). "In addition, miR-29c can function as a tumor suppressor by targeting VEGFA and inhibiting the tumor blood supply." (PMID 30948500, 2019). "Thus far, the VEGFA protein has been identified as a major factor that contributes to tumor angiogenesis and malignant progression in a variety of cancers." (PMID 31293831, 2019). "We predicted that JUN can regulate mononuclear cells to release VEGFA, which may promote tumor angiogenesis, which was proved as the reason for tumor initiation and progression." (PMID 31531018, 2019). "This is the first report to show that kindlin-2 could promote VEGFA secretion through the mTOR pathway and that this signalling pathway connects tumour cells with vascular endothelial cells." (PMID 31427543, 2019). "EYA4 overexpression suppressed the expression levels of c‐JUN and VEGFA in HCC tumours." (PMID 30957411, 2019). "Namely, it blocks tumor cell-mediated angiogenesis by downregulating VEGFA production, as well as Met and downstream angiogenic networks in some tumor models, while being required for efficient tube formation by EC and inflammation-induced angiogenesis in others." (PMID 31157165, 2019). "Moreover, VEGF family was considered plays a crucial role in tumor angiogenesis, and VEGFA mediates the leading role." (PMID 31498117, 2019). "Accumulating evidence indicates that monocytes (primarily iMo) are essential pre-metastatic promoters being rapidly recruited from the bone marrow to the pre-metastatic niche, mainly by CCL2/CCR2 axis, where they promote tumor colonization by secreting angiogenic factors, like VEGFA." (PMID 31447834, 2019). "Moreover, during β cell carcinogenesis, PLGF-1 reduces VEGFA-expression-dependent tumor angiogenesis." (PMID 30871059, 2019). "It is well-known that the IL-6/STAT3/VEGFA axis plays a key role in tumor angiogenesis." (PMID 30886152, 2019). "Thus, EHD1 overexpression leads to persistent β2AR signaling activity, and upregulated VEGFA stimulates tumor angiogenesis." (PMID 31023336, 2019). "VEGFA secreted by tumor cells, bind to VEGFR2 and promote neo-vascularization." (PMID 30858542, 2019).
tumor (continued). "In addition, VEGF-A (Vascular Endothelial Growth Factor-A), a pro-angiogenic factor crucial for tumor growth and progression, showed increased levels in TMZ-EVs group." (PMID 31597943, 2019). "The VEGFA levels in tumor supernatant were measured by ELISA." (PMID 30755242, 2019). "Additionally, miR-29c has been previously reported to inhibit the tumor blood supply by targeting VEGFA." (PMID 30948500, 2019). "In humans, vascular endothelial growth factor-A (VEGF-A) expression increases based on tumor grade." (PMID 30634402, 2019). "Indeed, VEGFA is the master mediator of tumor angiogenesis and stimulates the migration and proliferation of cultured endothelial cells in different cancer types." (PMID 31023336, 2019). "In addition, tumor can produce VEGFA, which increases expression of inhibitory immune checkpoints mediating T cell exhaustion on intratumoral CD8+ T cells." (PMID 31531018, 2019). "In these pathways, VEGFA was able to inhibit tumor angiogenesis in proteoglycans in cancer." (PMID 30936832, 2019). "These SNPs might interfere in the VEGFA expression, modulating the formation of vessels and facilitating the dissemination of tumor cells to other regions of the body." (PMID 30551681, 2018). "Indeed, E0771 tumors expressing VEGFA showed significantly increased microvascular density and tumor size in Peak1+/+ animals, compared to tumors derived from control E0771 cells or E0771 cells expressing GFP only." (PMID 29872538, 2018). "For instance, EGF plays an important role in tumour proliferation and metastasis; PDGFβ induces liver fibrosis and accelerates tumour development; VEGFA is one of the major growth factors responsible for angiogenesis; and IGF2 enhances tumour cell proliferation." (PMID 29346427, 2018). "As a matter of fact, VEGFA was initially purified from fluid secreted by a tumor." (PMID 30158456, 2018). "Our results demonstrated that the ERK/p70S6K/HIF-1α signalling pathway may be partially responsible for the UBE2CP3-induced accumulation of VEGFA and leads to tumor cell-mediated angiogenesis." (PMID 29866133, 2018). "Vascular endothelial growth factor A (VEGFA) is a crucial regulator of tumor vascularization and components of VEGF-induced cell signaling pathways are important targets of therapeutical drugs that demonstrated the highest efficiency in case of advanced HCC (sorafenib and regorafenib)." (PMID 29888133, 2018). "The HIF/VEGFA signalling pathway plays a central role in tumour angiogenesis." (PMID 30060750, 2018). "In particular, our results revealed that linc00511 may function as a ceRNA to mediate the expression of VEGFA through competition for hsa‐miR‐29b‐3p, hence serving as a tumour promoter in PDAC pathogenesis." (PMID 28984028, 2018). "High levels of pro-angiogenic VEGFA isoforms expression may contribute to sensitivity of tumor to anti-VEGFA drugs like bevacizumab." (PMID 29888133, 2018). "MiR‐29b regulation of VEGFA expression has been verified in various tumours." (PMID 28984028, 2018). "Furthermore, evidence indicates that ROS production induces VEGF-A (Vascular endothelial growth factor A) gene expression, related to angiogenesis, and can promote the metastatic growth of tumor cells." (PMID 30532780, 2018). "VEGFA/VEGFR2-dependent angiogenesis supports tumor growth in many human cancers." (PMID 29872538, 2018). "Additionally, TAMs have been shown to engage in a multicellular interaction with endothelial cells through the release of VEGFA to facilitate the intravasation of tumor cells from the primary site into circulation." (PMID 29946544, 2018). "However, VEGFA-121 overexpression can reduce tumor sensitivity to inhibitors of KDR receptor, particularly sorafenib, since VEGFA-121 mainly acts through alternative FLT-1 receptor (Rapisarda & Melillo, 2012; Vempati, Popel & Mac Gabhann, 2014)." (PMID 29888133, 2018).
tumor (continued). "To better understand the VEGF signaling requirements in tumor angiogenesis, we assessed whether Vegfr2, similar to VegfA, exerts gene dosage effect in tumor angiogenesis." (PMID 30283071, 2018). "Additionally, miR-34a transfection inhibited cell migration and tumor angiogenesis by downregulating VEGFA." (PMID 30563114, 2018). "In addition, recent studies have shown that tumour cells strongly promote blood vessel formation by secreting a diversity of angiogenic factors, such as VEGFA, PDGFB, bFGF and EGF8." (PMID 30584257, 2018). "Thus, evaluation of VEGFA isoforms expression pattern in tumor is important for a rational choice of anti-angiogenic therapy, which is considered to be a promising approach for HCC treatment." (PMID 29888133, 2018). "VEGFA is a proangiogenic cytokine that sustain tumour angiogenesis and limit antitumor immunity." (PMID 28984028, 2018). "Importantly, a series of rescue experiments suggested that the function of SIRT2 in tumour angiogenesis depends on the STAT3/VEGFA signalling pathway." (PMID 30584257, 2018). "Finally, as controls, we analyzed the mRNA expression of two hypoxia-inducible genes, VEGFA and CA9, and observed increased expression in the VHL-deficient tumor samples as expected." (PMID 29435132, 2018). "Other tumor-infiltrating immune cells, such as Tregs and mast cells, can also produce VEGFA." (PMID 30355585, 2018). "Further studies of VEGFA isoforms expression, VEGFA mRNA splicing regulation and VEGFA-189 functional properties in HCC are necessary in order to evaluate its possible association with other tumor progression factors, survival and recurrence." (PMID 29888133, 2018). "Along with low levels of CA9, this suggests that exponentially growing 231_HM.LNm5 tumours may experience less extreme hypoxia than the other tumour types and also that other factors may compensate for low VEGFA to promote angiogenesis." (PMID 29720474, 2018). "Meanwhile, VEGFA was also found to be markedly upregulated in other tumours." (PMID 28984028, 2018). "Moreover, in the context of tumour relapse after chemotherapy, MRC1hi, CXCR4hi, Tie2hi VEGFA+ macrophages have been identified as tumour-supporting M2 macrophages localising in perivascular areas where CXCL12 is expressed." (PMID 29760166, 2018). "VEGFA is expressed as a set of isoforms with different functional properties, thus VEGFA isoform expression pattern may affect tumor sensitivity to anti-angiogenic drugs." (PMID 29888133, 2018). "Furthermore, recent work by us and two other groups has shown that stress-responsive miR-153 suppresses tumor angiogenesis by inactivating the HIF1α/VEGFA axis under hypoxic conditions." (PMID 29959560, 2018). "The investigators found that poor tumor perfusion, as measured by multiparametric methods, correlated with high expression levels of vascular endothelial growth factor A (VEGFA) and immune checkpoints, cluster of differentiation 274 (CD274) and cytotoxic T-lymphocyte-associated-protein 4 (CTLA4)." (PMID 30591628, 2018). "VEGFA was recently shown to increase tumor‐initiating stem‐like cells in skin and breast cancers." (PMID 28179359, 2017). "TBP's ability to induce VEGFA production and the importance of VEGFA in driving tumor growth prompted us to investigate whether TBP expression is elevated in human tumors relative to normal tissue." (PMID 28415573, 2017). "BMI1 knockdown prevented the VEGFA‐mediated increase in tumor‐initiating cell abundance." (PMID 28179359, 2017). "Xenografts maintained maintained expression of tumour-derived VEGFA and stromal-derived COX-2." (PMID 28417956, 2017). "VEGFA binds to target receptor tyrosine kinases to induce signaling events important to its functions in normal physiology, development, and pathological states where it is a central player, including tumor angiogenesis." (PMID 28415573, 2017).